LEP (leptin)
Diseases named in the same sentence as LEP in open-access papers (continued):
Sharing a sentence is not in itself a finding about the gene and the disease.
Obesity (continued). "LEP downregulation of LEPR expression was suggested as one of the LEP resistant mechanisms for maintaining obesity." (PMID 33316917, 2020). "MC4R is a suitable candidate gene due to MC4R’s central position in the leptin–melanocortin pathway and given MC4R variants are among the most common cause of monogenic human obesity." (PMID 33233816, 2020). "Higher leptin concentrations were inversely proportional to left ventricular mass index and pulse wave velocity in patients with overweight and obesity." (PMID 32198598, 2020). "Dysregulation of the adipo-insular axis in obesity leads to a rise of basal plasma levels of insulin and leptin and development of compensatory peripheral tissue resistance to both hormones." (PMID 32092909, 2020). "The leptin-deficient ob/ob mice and DIO mice exhibit over-feeding and excessive energy uptake-derived obesity, and they are prone to many diseases like nonalcoholic fatty liver disease (NAFLD), hyperphagia, and type II diabetes." (PMID 32164196, 2020). "In the past two decades, many studies have explored the relationship between the abnormal expression of leptin and AdipoQ and various obesity-related cancers." (PMID 33256658, 2020). "Celastrol is a promising anti-obesity agent that acts as a sensitizer of the protein hormone leptin." (PMID 31992268, 2020). "Nutrients can change the expression of key genes related to obesity through DNA methylation; the leptin gene promoter methylation level changes correspondingly when the rats are given different diets." (PMID 33532487, 2020). "Leptin expression in mast cells from diet-induced obesity (DIO) WAT is higher than those from lean WAT." (PMID 32839413, 2020). "More recently, an independent research demonstrated that higher serum leptin concentrations coexisted with leptin resistance, and the disturbance was closely related to the development of obesity." (PMID 33597945, 2020). "In general, serum leptin levels in women are much higher than in men, and women possess a higher obesity rate than men." (PMID 33114326, 2020). "Patients with obesity and type 2 diabetes are usually hyperleptinemic and thus resistant to the effects of leptin therapy." (PMID 31743040, 2020). "LEP circulating levels are closely related to fat mass and LEP expression, and secretion is increased in obesity." (PMID 33316917, 2020). "In fact, due to high leptin levels among patients with obesity, leptin resistance can be the result of upregulation of SOCS‐3, which also negatively regulates antiviral interferons (INFs) signalling." (PMID 32583537, 2020). "Most individuals with obesity have leptin resistance by leptin and its receptor inhibitor SOCS-3 (suppressor of cytokine signaling-3), leading to dysfunction of leptin biological function." (PMID 33071815, 2020). "As is well established for HFD‐induced obesity in mice and obese humans, leptin signalling to the brain is disrupted and, consequently, its level in periphery is higher than in the healthy status." (PMID 32748559, 2020). "HFD-fed mice developed obesity with increasing in leptin secretion, which has been shown to negatively influence Leydig cell function." (PMID 32796811, 2020). "Leptin plays an important role in regulation of satiety and energy homeostasis, while adiponectin is an adipocyte-derived hormone that acts on anti-obesity, antidiabetic, and anti-inflammatory activity." (PMID 32397362, 2020). "The clinical significance of serum leptin and insulin levels in obesity has also been reported in the literature because of the positive correlation with an increase in body weight and fat mass." (PMID 33218042, 2020). "Unfortunately, the leptin resistance observed in obese rodents and humans has dismissed the idea of leptin as a possible treatment to treat obesity." (PMID 32069871, 2020). "It has also been reported that mice with whole body or neuron-specific deletion of PTP1B are hypersensitive to leptin, and are resistant to diet-induced obesity." (PMID 32630697, 2020).
Obesity (continued). "We then decided to examine the effects of long-term leptin treatment to see if this mild obesity in nPE1 KO mice was the result of leptin insensitivity." (PMID 33382813, 2020). "Obesity and pulmonary arterial hypertensionshare multiple pathophysiological mechanisms including inflammation, oxidativestress, elevated leptin (proinflammatory) and reduced adiponectin(anti-inflammatory)." (PMID 32999709, 2020). "Over the last years, the adipokine leptin has been well recognized as a key member of the molecular network linking obesity to breast cancer." (PMID 32727138, 2020). "The effect of obesity on measures of organ injury and on microbe, host inflammatory cytokine, and leptin levels was then examined in experiments providing data based on the type of infectious or septic challenge that was employed." (PMID 32211204, 2020). "In order to understand metabolic pathologies such as obesity or type 2 diabetes, genetically modified rodent models bearing alterations in leptin signalling pathway have been developed throughout the years." (PMID 32069871, 2020). "Firstly, the results of CRISPR-Cas9 leptin KO mice used in this study need to be compared and analyzed in other obesity models, including GEM obesity model with single autosomal recessive mutation of leptin gene and high-fat-diet-induced obese model." (PMID 33322729, 2020). "The first clinical trial that studied the potential pharmacological effects of leptin on polygenic or simple obesity dates back to 1999." (PMID 33192583, 2020). "In terms of obesity in women, leptin has been shown to correlate to an increase in mass accumulation in post-menopausal women, especially those that remained untreated with estradiol or other forms of hormone therapy." (PMID 32742493, 2020). "Studies in mice show that obesity induced by high fat diet or leptin deficiency result in overexpression of TLRs and related proinflammatory signaling molecules in enlarged adipose tissues, which may play an important role in the obesity-associated phenomenon of meta-inflammation." (PMID 33519463, 2020). "Serum leptin levels are directly proportional to the amount of adipose tissue and both increase progressively with obesity." (PMID 33334030, 2020). "In the last two decades, many studies show that the adipocyte-derived peptide hormone leptin plays an important role in linking obesity, inflammation, metabolic syndrome, and cardiovascular diseases." (PMID 32655492, 2020). "Obesity increases leptin and SNA, and as reviewed previously, some data suggest the two are functionally related in males." (PMID 32160920, 2020). "To further explore the possible role of leptin deficiency in promoting steatosis-enhanced metastasis, we administered breast cancer cells to mice fed a high-fat diet (HFD) for 12 weeks, producing obesity." (PMID 32879136, 2020). "In this study, leptin levels were significantly increased in children with overweight and obesity, as has consistently been observed in previous studies." (PMID 33261143, 2020). "In the present study, we investigated the genetic and environmental effects of LEP SNPs on obesity, obesity‐related metabolic traits, and leptin level." (PMID 31914480, 2020). "Elevated ceramides appear to worsen leptin resistance, which is an important phenomenon in the pathophysiology of obesity and metabolic syndrome." (PMID 33133017, 2020). "In fact, circulating leptin levels are proportional to body fat, but in diet-induced obesity, these increased levels fail to prevent weight gain." (PMID 32215011, 2020). "Leptin concentration in plasma is increased in obesity, and high levels of leptin lead to the production of pro-inflammatory cytokines, including TNF-α and IL-6." (PMID 32796637, 2020). "Other reviews also suggest that adiponectin, omentin, apelin, leptin, resistin, and fatty-acid-binding protein-4 were promising biomarkers for obesity." (PMID 32566274, 2020).
Obesity (continued). "Leptin-mediated reduced food intake subsequently inhibits obesity, hyperglycemia, and liver steatosis in HFD-treated male mice." (PMID 32733043, 2020). "Leptin, which has a similar action in obesity to that of insulin in diabetes, is a hormone that responds to fat deposition." (PMID 32906753, 2020). "Similar to MSG mice, ob/ob mice affect leptin signaling resulting obesity, hyperglycemia, and hepatic steatosis." (PMID 32103741, 2020). "High plasmatic levels of leptin are observed in obesity; however, obese individuals are resistant to the metabolic and respiratory effects of leptin." (PMID 32698380, 2020). "The increased leptin blood levels are strictly related to the metabolic dysfunction and pathological conditions observed during obesity, and in humans, hyperleptinemia can be considered a feature of MetS." (PMID 32851001, 2020). "Second, obesity-related hyperleptinemia and central leptin resistance are promoters of tumor invasiveness and migration." (PMID 33117814, 2020). "For instance, the use of diet-induced obesity animal models would mimic obesity’s general effects, whereas the use of more specific models such as db/db or ob/ob animal models would generate data closer to the effects of leptin in the obesity context." (PMID 33317011, 2020). "Here, we review the potential therapeutic ability of leptin to correct obesity and other metabolic disorders, not only through its satiating effect, but by also utilizing its thermogenic properties." (PMID 32069871, 2020). "Leptin and ghrelin not only affect food intake and glucose and lipid metabolism, but also reproductive physiology in obesity." (PMID 33088334, 2020). "The main differences were observed in the daily synthesis of leptin between the control subjects and the patients with obesity before treatment (pauc < 0.001)." (PMID 32230732, 2020). "Leptin in serum is elevated in the case of obesity as it functions to accelerate energy expenditure, whereas insulin levels are negatively correlated with adiponectin levels in 3T3-L1 preadipocytes." (PMID 33425000, 2020). "The reason obesity affects the pathophysiology of liver damage is likely related to the fact that leptin induces pro-inflammatory and angiogenic cytokines, thus altering the liver wound-healing response." (PMID 33520810, 2020). "The LEP system changes in the skin under obesity conditions however, the exact role of LEP in obese dog skin needs further insights." (PMID 33316917, 2020). "Leptin, of which levels are increased during obesity, regulates the inflammatory response at several levels (development, proliferation, maturation and activation) and fundamentally, it stimulates the production of pro-inflammatory cytokines." (PMID 32839413, 2020). "In this review, we discuss the role of adipokines in the onset of puberty in children with obesity during adrenarche and gonadarche and provide a clear and detailed overview of the biological processes of two major players, leptin and adiponectin." (PMID 32003144, 2020). "NCOA1L1376P knock-in mice bearing a mutation identified in obese patients show decreased leptin-induced depolarization of POMC neurons, increased food intake, and exacerbated obesity." (PMID 32449767, 2020). "The expression of genes, in particular, those related to the leptin–melanocortin system, fundamental for the regulation of energy homeostasis, involved in the development of obesity, is modulated by genetic factors and environmental factors." (PMID 33261141, 2020). "In particular, leptin plays an important role in obesity-related factors, such as body fat storage, and the regulation of body weight." (PMID 32709145, 2020). "The most contributing SNP to this consortium was rs1801253-ADRB1, as well as other obesity risk-associated SNPs (UCP2, ADIPOQ, LEP, MC4R, etc.)." (PMID 32398726, 2020).
Obesity (continued). "Among them, the so-called “obesity hormone” leptin, whose circulating levels increase in proportion to fat mass, has been extensively recognized for its role in influencing breast tumor biology." (PMID 32727138, 2020). "Leptin is also an adipose-derived protein related to appetite, obesity, energy balance, insulin resistance, and other metabolic parameters." (PMID 33551872, 2020). "According to some authors, in the course of evolution, leptin appeared as a factor protecting against hunger or obesity at times of availability of excess food." (PMID 32443588, 2020). "The adipokines, resistin and leptin were increased in mice induced to obesity by the HFD, while eriocitrin at 10, 25 and 100 mg/kg was able to moderately reduce resistin, but not leptin." (PMID 33489104, 2020). "Socs3 mRNA levels in the arcuate are increased after prolonged high fat diet exposure, while Socs3 deficiency or specific deletion of Socs3 in POMC neurons leads to enhanced leptin sensitivity and resistance to diet induced obesity." (PMID 33382813, 2020). "Obesity induces insulin, IGFs, leptin, IL-6, TNF-α, CCL2, and PAI-1, reduces adiponectin, and disturbs gut microbiota and bile acid homeostasis." (PMID 32486076, 2020). "We confirmed that leptin levels were higher in patients with endometrial cancer and obesity or diabetes compared to the control group, that is, burdened with these diseases." (PMID 32570721, 2020). "Shortly afterwards, a frameshift mutation in the human leptin gene (LEP) was identified in children with severe, early-onset obesity." (PMID 33233816, 2020). "We have chosen here to alter the endogenous leptin levels through physiological means, i.e., mainly by alterations in the degree of obesity, resulting in the expected alterations in leptin levels." (PMID 31743040, 2020). "Metabolic abnormalities within adipose tissue can contribute to obesity complications including excess adipokine secretion: visfatin, leptin, and resistin, but also TNF-α as and plasminogen activator inhibitor-1 (PAI-1)." (PMID 32963689, 2020). "PAC-rich extracts have also proved to be involved in obesity modulation (even at low doses) through the suppression of food intake and the increase in energy expenditure, possibly by mediating leptin levels." (PMID 32630697, 2020). "Role of leptin in obesity and insulin resistance and its effectiveness in the management of obesity is under many studies." (PMID 33489589, 2020). "Obesity is a significant risk factor and negative prognostic factor for breast cancer, and the adipocyte-derived adipokine leptin links obesity and breast cancer." (PMID 32836215, 2020). "Serotonin also shows negative correlations with inflammatory cytokines (IL-12 and IL-6), obesity (leptin and BMI), antioxidant status (GSH), and dyslipidemia-related markers (cholesterol, triglycerides, total/HDL), respectively." (PMID 33312720, 2020). "The development of hyperleptinemia and LEP resistance has been well documented in humans and domestic animals in overweight and obesity conditions." (PMID 33316917, 2020). "In obesity, circulating levels of leptin rise, although its ability to reduce food intake and to increase energy expenditure diminishes; hyperleptinaemia and inflammation have been postulated as causative mechanisms." (PMID 32825073, 2020). "Obesity is a chronic low-grade inflammation, and the concentrations of resistin, leptin, and IL-1β, as well as TNF-α and IL-6, in peripheral blood of obese patients were significantly increased." (PMID 32104715, 2020). "Recently, the same authors reported that preserving lower leptin levels in an obesogenic environment is highly beneficial for obesity and diabetes control." (PMID 32825073, 2020). "Higher leptin concentrations and decreased sensitivity to leptin can normally be found in people with obesity, and this hormone acts through the LEPR, the I-type cytokine receptor." (PMID 32517169, 2020).
Obesity (continued). "According to these authors, circulating serotonin interacts with leptin in the adipose tissue and increases the feeling of satiety; therefore, it is believed that serotonin has a protective role against obesity." (PMID 33081272, 2020). "Ghrelin and leptin are potent modulators of GLP-1 secretion by L-cells; both hormone systems are impaired occurring secondary to obesity, causing functional deficits in GLP-1 signaling." (PMID 33126672, 2020). "Conversely, the expression of leptin in basal cell carcinoma was very limited and reflected the irrelevant role of obesity in the induction of this kind of skin cancer." (PMID 33008429, 2020). "Increases in obesity-related immune activation and circulating leptin levels induce systemic IR, which greatly increases susceptibility to T2DM." (PMID 32920548, 2020). "The connection between obesity and chronic low-grade inflammation, leptin/adipokines and 11β-HSD1 activity has been discussed." (PMID 32947869, 2020). "The expression of PTP1B and T cell PTP (TCPTP) is upregulated in a high-fat diet and obesity, and inhibits leptin-mediated STAT3 phosphorylation." (PMID 32824322, 2020). "In this study, we found that administration of L. fermentum LM1016 suppressed diet-induced obesity and hepatic steatosis and improved serum metabolic markers, such as glucose, insulin, leptin, and cholesterol." (PMID 32917958, 2020). "Hypermethylation of gene promoter regions are associated with suppression of gene expression and these modifications, along with leptin resistance and obesity, can be inherited and passed to subsequent generations." (PMID 32407841, 2020). "A previous study demonstrated that a high-fat diet (HFD), administered for one-three-days, induces hypothalamic inflammation before obesity’s established, and the long term affects leptin signaling/action due to inflammation." (PMID 32576879, 2020). "Interesting novel developments are clinical trials with MC4R-agonists in patients with leptin-melanocortin pathway deficiencies, e.g. POMC and LEPR deficiency, and glucagon-like peptide 1 (GLP-1) agonists for adolescents with obesity." (PMID 32384097, 2020). "Among the adipokines, leptin and adiponectin are the most notable that are involved in immune modulation in obesity." (PMID 33086562, 2020). "Leptin resistance, a characteristic of severe obesity (BMI ≥ 35 kg/m2), due to impaired leptin transport across the blood–brain barrier, reduces the function of leptin receptors, and defects in leptin signal transduction." (PMID 31964368, 2020). "We found that circulating SIRT1 correlates well with visceral fat and has a greater R2 value in predicting FM compared with leptin and adiponectin in patients with obesity." (PMID 33202604, 2020). "As obesity progresses, proinflammatory adipokines, including leptin, TNF, resistin, IL-6, RBP4, lipocalin-2, and ANGPTL-2, are preferentially synthesized and cause chronic inflammation." (PMID 33133214, 2020). "These were accompanied by increased FI and lower energy expenditure (EE), leading to obesity, along with increased leptin and insulin levels and HOMA." (PMID 32576879, 2020). "In contrast, in males, obesity preserves or enhances the central sympathoexcitatory response to leptin, and current evidence favors leptin’s contribution to the well-established increases in SNA induced by obesity in men." (PMID 32160920, 2020). "The obesity-related changes in the feeding behavior of the MSG-treated mice are possibly the result of missing leptin and insulin receptors in ARCs and consequent altered neuropeptide signaling." (PMID 33324348, 2020). "In fact, up-regulation of SOCS3 in proopiomelanocortin (POMC) neurons leads to impairment of STAT3 signaling, with consequential leptin resistance and obesity, as well as glucose intolerance." (PMID 32630697, 2020).